RN7SL381P (RNA, 7SL, cytoplasmic 381, pseudogene)
Gene: Miscellaneous RNA gene on chromosome 16 (85,659,378 to 85,659,675, forward strand). Ensembl gene ENSG00000263968.
Homologues: Orthologues: chimpanzee Metazoa_SRP (99% identical), macaque Metazoa_SRP (89% identical). Paralogues in human: RN7SL2 (86% identical), RN7SL1 (85% identical), RN7SL3 (84% identical), RN7SL357P (82% identical), RN7SL230P (82% identical), RN7SL481P (81% identical), RN7SL664P (81% identical), RN7SL14P (81% identical), RN7SL47P (81% identical), RN7SL543P (81% identical), RN7SL88P (81% identical), RN7SL492P (80% identical), and 704 more.